LINC00648 (long independently transcribed non-coding RNA 648)
Gene: Long non-coding RNA gene on chromosome 14 (47,682,429 to 47,901,681, reverse strand). Ensembl gene ENSG00000259129.
Diseases named in the same sentence as LINC00648 in open-access papers:
LINC00648 is named in the same sentence as 1 disease in open-access papers, as found by Europe PMC text mining. Sharing a sentence is not in itself a finding about the gene and the disease.
LINC00648 shares sentences with these, for which no sentence is quoted: lung carcinoma (1 paper).